APOE (apolipoprotein E)
Diseases named in the same sentence as APOE in open-access papers (continued):
Sharing a sentence is not in itself a finding about the gene and the disease.
atherosclerosis (continued). "We found that MALAT1 was dysregulated in arterial tissues from ApoE−/− mice with high-fat food-induced atherosclerosis and human umbilical vein endothelial cell line (HUVECs) stimulated with ox-LDL." (PMID 30871555, 2019). "In ApoE−/− mice which induced atherosclerosis by a high‐fat diet, RBC membrane cloaked nanoparticles accumulated in established atherosclerotic plaques." (PMID 31380165, 2019). "Studies from the authors’ laboratory have recently uncovered evidence linking cellular apoE expression to enhanced miR-146a levels in macrophages and monocytes that suppress inflammation and atherosclerosis in hyperlipidemic mice." (PMID 29789495, 2018). "For atherosclerosis studies, the hyperlipidemic apolipoprotein E-null (ApoE−/−) mice on a high-fat diet are frequently used to generate vascular lesions." (PMID 29849882, 2018). "The aim of the present work was to examine the effects of AT1R deficiency within BM-derived cells on Ang II-induced advanced atherosclerosis and plaque vulnerability using the 2K1C apoE−/− mouse model." (PMID 30181481, 2018). "It has been reported that activation of PXR by a PXR agonist increases the levels of atherogenic lipoproteins VLDL and LDL, and that PXR activation accelerates atherosclerosis in ApoE-/- mice." (PMID 30319417, 2018). "Quantification of atherosclerosis in aortic preparations stained with Oil red O revealed a significant 71% decrease in atherosclerotic plaque surface in 2K1C AT1aR−/− → ApoE−/− mice compared to control ones (0.29 ± 0.04% versus 1.01 ± 0.21%)." (PMID 30181481, 2018). "Because of its potent ability to reduce plasma lipid levels in rodents, investigating how elevated apoE levels contribute to regulate atherosclerosis in the setting of hyperlipidemia has been challenging." (PMID 29789495, 2018). "Apolipoprotein E (apoE) knock-out (KO) mice are frequently used for the study of hyperlipidemia and atherosclerosis." (PMID 30021609, 2018). "The anti‐atherogenic properties of apoE are utilized in apoE knockout mice where the atherogenic process is speeded up, enabling studies of mechanisms involved in atherosclerosis and disease development." (PMID 29341140, 2018). "The ApoE−/− mouse is a transgenic model of atherosclerosis, having significant defects in the homeostasis of cholesterol and other lipids." (PMID 30061606, 2018). "Although macrophages are recognized as the main source of apoE in atheroma, newer findings have reported apoE expression by monocytes as a contributing source of hyperlipidemia and atherosclerosis regulation." (PMID 29789495, 2018). "To test the effect of vaccination on atherosclerosis we examined the brachiocephalic arteries and aortic arches from 34 week-old ApoE-/- mice as these arteries consistently had macroscopically visible plaque formation in the control animals." (PMID 29641559, 2018). "In conclusion, despite a similar induction level of Cyp3a11 expression in the liver, RIF had a different effect on plasma lipids and atherosclerosis development in young ApoE KO and het mice, revealing the importance of Cyp27a1 gene dosage in vivo in mice." (PMID 29191818, 2018). "Next, iron oxide MNPs were injected into wild-type mice, for the control group, and ApoE KO mice, a widely-used atherosclerosis model, and in vivo imaging was performed." (PMID 29795012, 2018).
atherosclerosis (continued). "The 2-kidney, 1-clip (2K1C) model (Ang II-dependent mouse model of advanced atherosclerosis and vulnerable plaques) was generated in ApoE−/− mice transplanted with AT1aR−/− or AT1aR+/+ BM." (PMID 30181481, 2018). "Elevated levels of circulating apoE in the hyperlipidemic plasma of Apoeh/hLdlr−/− mice led to a significant reduction in atherosclerosis in both the aortic root and the abdominal aorta of 5-month-old mice." (PMID 29789495, 2018). "The extent of atherosclerosis was significantly larger in the aortic arch of ApoE KO mice exposed to the high dose of CS than the control and the low dose." (PMID 29642385, 2018). "Atherosclerotic lesion was evaluated to demonstrate the effectiveness of ApoE gene knockout fed with WD and exercise training on the development of atherosclerosis in aorta." (PMID 29784903, 2018). "Pre-existing hyperlipidemia and atherosclerosis in ApoE−/− mice facilitate AngII-induced AAA formation." (PMID 30413751, 2018). "Regarding in vivo atheroprotective effects, chili pepper triggered TRPV1 activation to reduce vascular lipid accumulation and attenuate atherosclerosis in ApoE−/− mice fed an HFD." (PMID 30423840, 2018). "It is extremely sensitive to altered lipid flux driven by dyslipidemias and prolonged alteration in lipid flux can lead to hepatic steatosis in conjunction with atherosclerosis, as can be seen in the apoE-/- model with age." (PMID 30596094, 2018). "The administration of L. acidophilus ATCC 4356 was found to protect against atherosclerosis in ApoE knock-out mice through the inhibition of intestinal cholesterol absorption." (PMID 29402949, 2018). "Beyond its pivotal role in regulating lipoprotein cholesterol transport, apoE is recognized for its capacity to suppress atherosclerosis by exerting multiple effects on almost every cell type found in the arterial wall." (PMID 29789495, 2018). "An FXR agonist inhibited the expression of CYP7A1 and CYP8B1 in ApoE-/- mice and protected mice against atherosclerosis." (PMID 30319417, 2018). "Preclinical studies using animal models of atherosclerosis to explore this phenomenon have demonstrated that administration of aldosterone to apolipoprotein E knockout (ApoE−/−) mice accelerates atherosclerosis and plaque inflammation." (PMID 30038907, 2018). "In apoE‐deficient mice, deletion of CD40 or CD40L leads to attenuation of atherosclerosis, increasing ECM and preferential polarization towards the anti‐inflammatory M2 phenotype 113." (PMID 29364567, 2018). "Endothelial dysfunction is an initial parameter of atherosclerosis and the impaired endothelial function of resistance vessels in the ApoE KO mice is characterized by reduced NO bioavailability." (PMID 29784903, 2018). "To this context, we investigated for the first time the effects of long-term treatment with canagliflozin on atherosclerosis development in the aorta of APOE(−/−) mice as well as on biochemical and immunohistochemical markers linked to atherosclerosis." (PMID 30049285, 2018). "The effects of SSE on blood lipids and the development of atherosclerosis are currently under investigation using appropriate models, such as the ApoE KO mice." (PMID 29768504, 2018). "Active immunization with PCho and passive immunization with anti-PCho ameliorate the development of atherosclerosis in apolipoprotein E-null mice." (PMID 29329335, 2018).
atherosclerosis (continued). "The classical markers of autophagy, including LC3-II, p62/SQSTM1, and Beclin-1, have been identified by immunoblot and immunofluorescence microscopy analysis in both human atheroma lesions and in ApoE-null mice that spontaneously develop atherosclerosis." (PMID 30249977, 2018). "Initial studies about the atherosclerosis treatment with GF showed that gardenia inhibited the development of atherosclerosis in ApoE-knockout mice." (PMID 30574425, 2018). "The relationship between vasculature and morphological alterations in different organs was investigated more systematically in a mouse model of atherosclerosis (ApoE−/−/LDL receptor−/− mice) displaying enhanced plasma cholesterol levels." (PMID 29615651, 2018). "Nicotine promoted atherosclerosis in ApoE−/− mice, which was attenuated by GTPCH1 overexpression or BH4 supplementation." (PMID 30091833, 2018). "In apolipoprotein E deficient (apoE−/−) mice, IL-20 is able to enhance IL-6 and TNF-α expression and accelerate the development of atherosclerosis." (PMID 29690863, 2018). "Apolipoprotein E (ApoE) plays an critical role in the metabolism of lipoproteins and redistribution of cholesterol, and has long been studied in relation to atherosclerosis and cardiovascular disease." (PMID 29962946, 2018). "It is well known that apoE KO mice can develop atherosclerosis even on a normal chow diet and moreover, a Western diet is very atherogenic and accelerates the development of atherosclerosis in apoE KO mice." (PMID 30021609, 2018). "The apoE from transplanted bone marrow cells is able to rescue the hyperlipidemia as well as the atherosclerosis of the Apoe−/− recipients." (PMID 30404132, 2018). "Here, we successfully established novel porcine models of accelerated atherosclerosis in Bama miniature pigs by disrupting the endogenous ApoE gene using the CRISPR/Cas9 system." (PMID 30305304, 2018). "In experimental studies, drinking water supplemented with EGCG evidently inhibited high-fat-diet (HFD)-induced atherosclerosis in ApoE-knockout (ApoE-/-) mice." (PMID 29593532, 2018). "Remarkably, infusions of apoE-responsive microRNA mimics were shown to substitute for apoE in protecting against systemic and vascular inflammation to suppress atherosclerosis in mice with hyperlipidemia." (PMID 29789495, 2018). "In our recently published manuscript, we found that global miR-155 deletion in an atherosclerotic mouse background (ApoE knockout mice) improved atherosclerosis but resulted in obesity, NAFLD, and hyperinsulinemia without insulin resistance." (PMID 30369883, 2018). "Deletion of both ApoE and Tollip disturbed the fusion of lipid droplets with lysosomes in aortic macrophages and hepatocytes, and aggravated atherosclerosis and hepatic steatosis, compared to deletion of ApoE alone." (PMID 29774216, 2018). "In this subject, it has been demonstrated that LHRD ameliorated atherosclerosis through inhibition of atherosclerotic lesions and plaque formation both in aortic roots and aortic trees of ApoE−/− mice fed with western diet." (PMID 30402125, 2018). "Collectively, findings of apoE-regulation of microRNA signaling provide new mechanistic properties to explain its capacity to suppresses atherosclerosis beyond reducing plasma lipid levels or enhancing cellular lipid efflux." (PMID 29789495, 2018). "Genetic knockout of ANGPTL4 protects APOE−/− mice against development of atherosclerosis and strongly suppresses the ability of the macrophages to become foam cells." (PMID 29940978, 2018). "In this study, we intend to further investigate the molecular mechanism of BSKS against atherosclerosis in ApoE−/− mice." (PMID 29619063, 2018). "Atherosclerosis is ameliorated in ApoE-/- mice in which the CX3CL1/CX3CR1 pathway has been genetically deleted or pharmacologically blocked." (PMID 29641559, 2018).
atherosclerosis (continued). "While hepatic derived apoE is associated to very low density lipoprotein (VLDL) and contributes to their catabolism, leading to atherosclerosis in apoE KO mice, myeloid-derived apoE is present on nascent HDL." (PMID 30082772, 2018). "They showed that TLR3−/−ApoE−/− mice developed atherosclerosis earlier than TLR3+/+ApoE−/− counterparts, suggesting that TLR3 is a protective factor." (PMID 30225265, 2018). "Mutations in the apoproteins that function as ligands for the LDL receptor (e.g. apo B-100 and apoE) can cause high LDL concentrations and an increased risk of atherosclerosis." (PMID 30509933, 2018). "Mice and humans lacking apoE exhibit increased levels of plasma cholesterol promoting atherosclerosis, which confirms the importance of apoE in the metabolism of lipoproteins." (PMID 29341140, 2018). "The recombinant IL-6 aggravates atherosclerosis in apoE-/- mice and inhibition of IL-6 trans-signaling reduces atherosclerosis whereas other studies show atheroprotective properties of IL-6." (PMID 29329335, 2018). "We recently reported that DBZ inhibits foam cell formation and protects against atherosclerosis in ApoE−/− mice through activating LXRs." (PMID 29690611, 2018). "We have now shown that cell-specific deficiency in endothelial cell and leucocyte BH4 is sufficient to accelerate atherosclerosis in ApoE–/– mice." (PMID 29596571, 2018). "In spite of this, there were no aortic lesions in WT mice on both a chow and Western diet but atherosclerosis was observed in apoE KO mice on both a chow and Western diet." (PMID 30021609, 2018). "The expression of miR-26a was markedly reduced in atherosclerosis mice when compared to that in apoE−/− mice fed with a normal diet, as demonstrated by RT-qPCR." (PMID 29387339, 2018). "In the present study, we investigated the effects of BM on the development of atherosclerosis induced by HFD in ApoE-/- mice and explored the potential mechanisms." (PMID 30400958, 2018). "A recent study demonstrated that valsartan attenuates atherosclerosis via an increase in Th1 and Th17 and a decrease in Th2 and Treg cells in prolonged Ang II-treated ApoE−/− mice." (PMID 30181481, 2018). "In ApoE(-/-) mice, H2S inhibits proliferation and migration of VSMCs and inhibits the development of atherosclerosis by increasing plasma NO levels and increasing levels of S-nitrosylated proteins in VSMCs." (PMID 30298008, 2018). "Mechanistically, compared with ApoE–/– mice, SMC-specific PTEN-null/ApoE–/– double-knockout mice exhibited accelerated atherosclerosis progression and increased vascular fibrosis." (PMID 29467331, 2018). "We reported that microRNA-155 (miR-155) deficiency in ApoE-/- mice yields a novel metabolically healthy obese (MHO) model, which exhibits improved atherosclerosis but results in obesity, non-alcoholic fatty liver disease (NAFLD) without insulin resistance." (PMID 30369883, 2018). "Glucose uptake was increased in atheromatous plaques, spleens, and the bone marrow of the ApoE−/− mouse model of atherosclerosis." (PMID 28971272, 2018). "Through determining CHOP expression (amongst other markers) in MOs from early fatty streaks and advanced lesions, ER stress was manifestly elevated during the progression of atherosclerosis in chow- or Western diet-fed ApoE−/− mice." (PMID 29997514, 2018). "The unique phenotype of inducible apoE expression displayed by HypoE mice offered new opportunities to investigate the importance in the source of apoE in the process of atherosclerosis." (PMID 29789495, 2018). "Sustained expression of apoE in the vessel wall in a murine model of macrophage death suppression established the importance of this source of apoE in atherosclerosis control." (PMID 29789495, 2018).
atherosclerosis (continued). "When the relative amount of atherosclerotic plaque was considered, RIF reduced atherosclerosis formation by 66% in ApoE KO mice and by only 38% in het." (PMID 29191818, 2018). "CD100 roles in atherosclerosis were evaluated both in LDL−/− and apolipoprotein E deficient (ApoE−/−) mice models, as well as in an injury model of thrombus formation." (PMID 30324109, 2018). "FCs in Freund's adjuvant were then subjected to subcutaneous injection in ApoE−/− mice with developing or established atherosclerosis." (PMID 30687328, 2018). "In accordance with these results, in the present study, apoE−/− mice directly administrated with TMAO for 8 weeks also showed notable progression of atherosclerosis." (PMID 30567573, 2018). "Subsequent studies have shown a similar effect in atherosclerosis-prone mice that lack the apolipoprotein-E gene (ApoE−/−) when fed a diet containing mixed CLA, or a CLA diet containing 80% 9,11 CLA and 20% 10,12 CLA." (PMID 30282904, 2018). "Here we applied the QDSP protocol to ApoE knock out mice (ApoE−/−), a classical mouse model for atherosclerosis." (PMID 29208753, 2018). "In contrast, EC-FGF receptor signaling accelerates atherosclerosis, whereas EC-overexpression of FasL decreases atherosclerosis in ApoE−/− mice." (PMID 30406116, 2018). "The rationale for testing this in the ApoE−/− mouse model is based on multiple studies showing that aldosterone enhances, and MR antagonists inhibit, atherosclerosis in this model." (PMID 30038907, 2018). "Collectively, such recent findings broaden our understanding and appreciation for apoE in its capacity to suppress atherosclerosis beyond modulating plasma and cellular lipid levels." (PMID 29789495, 2018). "Our research showed that in ApoE null mice, pu-erh tea impeded the progress of atherosclerosis by promoting the apoptosis of macrophages in the atherosclerotic plaque." (PMID 30210650, 2018). "Herein, we investigated the effects of long-term treatment with canagliflozin on biochemical and immunohistochemical markers related to atherosclerosis and atherosclerosis development in the aorta of apolipoprotein E knockout (Apo-E(−/−)) mice." (PMID 30049285, 2018). "ApoE null mice are classic animal models used for studying atherosclerosis, in which the mechanism for arterial plaque formation came from spontaneous hypercholesterolemia." (PMID 30210650, 2018). "This study explored, for the first time, the role of the MR specifically in SMCs in the process of atherosclerosis using the ApoE−/− mouse model." (PMID 30038907, 2018). "Although the role of Gal-1 in atherosclerosis has not yet been examined in detail, Gal-3 blockade led to reduced atherosclerosis in ApoE−/− mice." (PMID 30524200, 2018). "H2S can also inhibit atherosclerosis in ApoE(-/-) mice as well as the proliferation and migration of vascular smooth muscle cells (VSMCs) by upregulating plasma NO." (PMID 30298008, 2018). "Genetic deletion of Nox4 in ApoE−/− mice increased atherosclerosis after 20 weeks of diabetes mellitus induction, while deletion of Nox1 in the same conditions reduced atherosclerosis." (PMID 29710840, 2018). "Using conditions to prevent GH release, we have determined that long-term treatment with GHRPs markedly decreased plaque formation in apoE-null mice fed a high-fat diet, a model known to develop atherosclerosis." (PMID 29883404, 2018).